AR (androgen receptor)
Diseases named in the same sentence as AR in open-access papers (continued):
Sharing a sentence is not in itself a finding about the gene and the disease.
tumor (continued). "Canine PCs commonly exhibit spontaneous metastasis, loss of androgen receptor (AR) expression, and the expression of proteins such as NKX3.1 and PTEN, which are associated with aggressive tumor behaviors in dogs and are also found in CRPC." (PMID 39453093, 2024). "AHR upregulates AR target genes that are involved in tumor proliferation, further complicating treatment strategies." (PMID 39600743, 2024). "We confirmed the predominant role of tumor genetic alterations converging on augmenting androgen receptor (AR) signaling and the increased transcriptional heterogeneity and lineage plasticity during the emergence of ARSI resistance." (PMID 39352383, 2024). "Oral administration of ARD-2128 effectively lowers AR protein levels and downregulates AR-targeted genes within tumor tissue, significantly inhibiting tumor growth in mouse models." (PMID 38675453, 2024). "PCa is a hormone-driven tumor and most advanced PCa patients are ‘homogeneously’ treated by hormone blockade using inhibitors of testosterone production and AR signaling." (PMID 39363904, 2024). "Elevated levels of AKR1C3 activate androgen receptor (AR) signaling pathway, contributing to tumor recurrence and imparting resistance to cancer therapies." (PMID 38523637, 2024). "Several genes from multiple families have been identified as possible biomarkers for disease, including those from the MYC and ETS families, as well as several tumour suppressor genes, Androgen Receptor signalling genes and DNA repair genes." (PMID 39410867, 2024). "ING1 and ING2, key components in mSIN3a-HDAC complexes, actively repress cell proliferation and tumor growth, also modulating hormonal-epigenetic interplay via androgen receptor signaling." (PMID 38813086, 2024). "ING1 and ING2, for example, modulate cell cycle arrest and apoptosis through androgen receptor signalling, contributing to tumor suppression." (PMID 38813086, 2024). "As we examined tumor sites within the 22 adrenal metastasis samples, it was clear that HSD3B1 and CYP3A43 exhibited robust association with AR expression (R = 0.7 and 0.56), whereas the rest of the APUC-6 genes did not." (PMID 39207857, 2024). "The proportion of tumor cells expressing nuclear AR was higher in spheroid primary tumors (over 60%) than in monolayer primary tumors (45%, p = 0.11)." (PMID 38632341, 2024). "Studies have shown that a variety of cytokines, kinases and downstream signaling factors promote the growth of tumor cells through the interaction of AR or androgen-independent pathway." (PMID 37716981, 2023). "The median percentages of tumor-infiltrating lymphocytes (TILs) in the AR+ group and AR− group were 30% (IQR: 20–45) and 37.5% (IQR: 20–67.5), respectively." (PMID 37085500, 2023). "In a multivariate analysis including pT, pN, and tumor grade, a high expression level of PR (mfIHC score > 15 vs. <15, HR 0.55, p = 0.0149) and AR (mfIHC score > 23 vs. <23, HR 0.54, p = 0.0151) expression were independent predictors of overall survival." (PMID 38137396, 2023). "This indicates that CRPC harboring a high diversity of AR gene rearrangements has less intra-tumor heterogeneity than would be expected from a scenario where different AR gene rearrangements occur in different CRPC cells." (PMID 37636316, 2023). "Immunohistochemical (IHC) analysis found that AR expression is higher in tumor tissue from males than from females." (PMID 37626712, 2023). "Animal studies utilizing AR-positive RCC tumor cells show that treatment with enzalutamide or limiting DHT production with abiraterone acetate significantly reduces tumor growth." (PMID 37626712, 2023). "While AIs effectively block the conversion of androgens to estrogens to decrease ER-stimulated tumor growth, over time, circulating and intra-tumoral androgens can increase as an unintended consequence, resulting in AR activation and resistance to AI therapy." (PMID 37210417, 2023).
tumor (continued). "Under the pressure of targeted inhibitors of the AR pathway, sub-clonal cells that can adapt to the environment become the main cells inside the tumor and finally complete the transformation of tumor pathological types." (PMID 36959803, 2023). "The presented results finally lead to a main clinical consequence: virtually all cells expressing AR-Vs also express high levels of AR-FL, which still implies tumor cell vulnerability to ARTA treatment." (PMID 37016463, 2023). "In castration-resistant prostate cancer (CRPC), despite reduced serum testosterone levels, AR signaling is therefore persistently activated to drive tumor progression." (PMID 37958994, 2023). "In treated tumours, it is believed that NED is driven by selection pressure induced by treatment associated with reduced AR activity or expression." (PMID 37740039, 2023). "Using FISH for AR and the chrX centromere, we confirmed AR ecDNA staining in all nuclei of LuCaP 105CR tumor cells from castrated mice." (PMID 37636316, 2023). "Castration reduces androgen receptor (AR) activity and tumor growth (post-castration group, POST-CX)." (PMID 38105227, 2023). "Mechanistically, FOXP1 gene generally mapped to a tumor suppressor locus at 3p14.1, repressed AR-induced transcriptional activity or histone modification, and interacted between FOXP1 and NFAT1." (PMID 36952469, 2023). "The results show that hepatoid adenomas that are characterized by high expression of AR and ER receptors respond positively to antihormonal therapy, resulting in complete tumor regression." (PMID 36766353, 2023). "It is also worth determining if CHD1 inhibitors synergize with AR or GR inhibitors in suppressing CRPC tumor growth and progression." (PMID 36776288, 2023). "HSD172B2 encodes 17βHSD, a tumor suppressor preventing the conversion of precursors to DHT and inhibiting AR signaling." (PMID 37370750, 2023). "Emergence of multiple AR protein species in this ∼60–80 kDa size range was also observed in LuCaP 35CR tumor tissue." (PMID 37636316, 2023). "In Part 1 of the protocol, patients had tumor samples profiled with targeted next generation sequencing as well as immunohistochemistry for androgen receptor, HER‐2 and ALK." (PMID 37818869, 2023). "In most cases, AR signalling remains essential for the maintenance and progression of the tumour, although, as is also found in SCs after mating, its activation no longer requires androgens." (PMID 37363926, 2023). "The combination of androgen and AR occurs in the nucleus, so the distribution and metastasis of AR in cytoplasm and nucleus are closely related to the proliferation of tumours." (PMID 37431884, 2023). "A previously established AR signaling score, which includes gene signature changes resulting from pathway stimulation, can be used as a metric of AR activity in tumor material." (PMID 36724278, 2023). "There is evidence that testosterone supplementation impairs the reduced antitumor activity of DTX and that AR activation reverses the tumor regression of DTX treatment." (PMID 37660001, 2023). "In metastatic, castration-resistant PCa, ~17–20% are histologically classified as SCNC5, consisting of tumor cells that show NE differentiation and are completely unresponsive to hormonal therapy due to inactivation of AR signaling." (PMID 36828904, 2023). "Androgen receptor (AR) can suppress tumor cell proliferation through suppressing ERα signaling of ER-positive BC, thereby promoting ER-negative BC cell growth." (PMID 37251574, 2023). "There was also a trend that HER2+HR− breast IDC patients who had positive PD-L1 in both tumor cells and immune cells with high AR expression had a longer DFS and OS than those with low AR expression." (PMID 37085500, 2023).
tumor (continued). "As expected, tumours with AR knockdown showed decreased tumour growth as compared with the 22Rv1‐Ctrl group (p < 0.05)." (PMID 37326412, 2023). "Lately, it has also been suggested that the AR is involved in tumor cell immune evasion, resulting in a lower immune response and thus a lower chance of achieving a pCR." (PMID 36769287, 2023). "We also categorized each patient tumor and mPC model into phenotypic categories based on gene expression signatures reflecting AR signaling and neuroendocrine (NE) pathway activity." (PMID 37725435, 2023). "Noteworthy, previous studies employing AR FISH with circulating tumor cells (CTCs) from CRPC patients often observed punctate AR staining patterns, at frequencies similar to HSR staining patterns." (PMID 37636316, 2023). "These three AR antagonists demonstrated appreciable efficacy in prolonging the patient’s survival time, as well as tumor progression time, by binding to the AR LBD and turning the AR switch to “off” status." (PMID 37375297, 2023). "In the prostate LNCaP cell line, non-DNA-binding-dependent actions of androgens through membrane AR led to apoptosis and the reduction of tumor size." (PMID 37626712, 2023). "In BPH, kaempferol is known to suppress tumor development by inhibiting the activity of the androgen receptor (AR) and exerting a significant anti-benign effect." (PMID 37893729, 2023). "Mice with LNCaP subcutaneous tumours treated with combination AR and PKA oligodeoxynucleotides over four weeks had significantly reduced tumour mass compared with control (P = 0.008)." (PMID 37830741, 2023). "THZ1 inhibits tumor growth and reverses the drug resistance phenotype associated with hyperphosphorylated MED1 by blocking androgen receptor/MED1 corecruitment." (PMID 36875159, 2023). "In PCa, the strong reliance of cells on AR signaling has been exploited in the development of therapeutics, which target the LBD to limit AR signaling, restricting tumor growth." (PMID 36720985, 2023). "Current evidence suggests that the AR can positively and negatively regulate processes that maintain CSCs, depending on the tumor context." (PMID 37894767, 2023). "Increased intracellular ROS after AR silencing confirms the significant role of AR signaling in oxidative stress regulation in the tumor microenvironment during PCa progression." (PMID 38155939, 2023). "The effects of the AR on cell proliferation and tumor progression are unclear because its action depends on the co-expression of ERα in BC." (PMID 37894767, 2023). "Using a fusion FISH strategy, we confirmed that many of the AR ecDNA molecules in LuCaP 105CR tumor cells had signal that overlapped with signal for the chr16 amplicon region at 16p11.2 in LuCaP 105CR tumor cells." (PMID 37636316, 2023). "The androgen receptor (AR), an important protein in several tumor types includingprostate, breast, and bladder and correlated with the Uc.63 expression; had its expression disrupted by Uc.63modulation in BlC cells." (PMID 36622962, 2023). "NDRG1, an α/β-hydrolase, is described to have a tumor suppressive character in PCa and to be involved in the regulation of androgen receptor signaling." (PMID 37671061, 2023). "These neoplasms can still be treated with next-generation AR pathway inhibitors (e.g., enzalutamide and abiraterone) and/or with taxanes." (PMID 36674949, 2023). "The relationships between them and the expressions of ER, PgR, and AR of tumor tissues, evaluated immunohistochemically, were analyzed." (PMID 36721218, 2023). "Additional molecular findings were low to medium HER2-expression in 3 patients, PD-L1 expression in 2 patients, a tumor mutational burden (TMB) > 10 mutations/Megabase (mut/Mb) and an AR mutation in 1 patient, each." (PMID 37427101, 2023). "Inhibition of fatty acid synthesis in metastatic castration resistance PC xenograft and organoid model, reduced tumor growth by downregulate androgen receptor pathways." (PMID 37256171, 2023).
tumor (continued). "Tumor cells can escape inhibition of androgen synthesis by goserelin or abiraterone by increasing, intratumorally, androgen synthesis and/or AR, but also via glucocorticoid receptors and glucocorticoids." (PMID 36769263, 2023). "Resveratrol reduces CRPC tumor progression by repressing β-CATENIN-mediated AR signaling and inhibiting the nuclear translocation of β-CATENIN through the suppression of the HIF-1 expression level." (PMID 37895357, 2023). "Another member of the RAS pathway, the angiotensin II receptor type 1 (AGTR1) was also associated with metastatic PCa cells, while the angiotensin II receptor type 2 inhibits tumor growth, induces apoptosis, and reduces Ki‐67 and AR expression." (PMID 36329628, 2023). "It offers a clinical opportunity for novel agents targeting AR-Vs expression to prohibit CRPC tumor growth." (PMID 37242518, 2023). "Specifically, our results revealed that 5α-reductase inhibition attenuate tumor progression by inhibiting the conversion of testosterone to DHT in the presence of membrane AR in BCa." (PMID 36800968, 2023). "ERα and AR proteins were elevated in malignant tumor tissues, and ERβ and progesterone receptor (PR) were significantly decreased." (PMID 38115900, 2023). "In GELATO, four of five patients with TN-ILC had ER+ primary tumors, and all patients with TN-ILC had positive AR IHC expression (≥10% of tumor cells)." (PMID 37038006, 2023). "The expression correlation of TOMM20 and AR in PCa was determined by analyzing publicly available datasets, or by IHC staining in tumor specimens." (PMID 37563661, 2023). "The study showed that the effect of antihormonal treatment depended on the histological type of the tumor and, thus, the expression levels of AR and ER receptors." (PMID 36766353, 2023). "A significantly higher expression of MYB and AR were observed in the tumor cells those were invaded into extraprostatic extension (pT3a), seminal vesicle (pT3b), or bladder and/or rectum (pT4) compared to prostate confined (pT2-pT2c) tumor." (PMID 38089573, 2023). "It was shown that AR protein expression is detectable in BC tumor tissue, however with a higher prevalence in ER-positive tumors (75–85%) than TNBC tumors (30%)." (PMID 38001722, 2023). "FOXO1 is a transcription factor for tumor suppressor, which is inactivated in tumor cells and acts as a target of the AR/ERβ pathway." (PMID 36732762, 2023). "AR expression was highest in male tumor tissues, where AR receptor blockers induced apoptosis and testosterone co-treatment impeded the effect." (PMID 38115900, 2023). "Our results show that reduced AB56αC heterotrimers lead to increased AR activity and castration-resistant tumor growth in vivo." (PMID 37644036, 2023). "We found that in LUAD, compared with normal tissues, AR was significantly positively correlated with TMPRSS2 in tumor tissues, this was also confirmed in the protein expression levels of TMPRSS2 in different sexes." (PMID 36992839, 2023). "Targeting steroid hormonal receptors, such as ERβ, GR, and AR, has shown some potential in inhibiting cancer cell proliferation and curbing tumor growth in biological models." (PMID 37835396, 2023). "As NEPC tumours diminish the AR signalling regulating many metabolic processes in PCa, activation of several signal pathways and epigenetic modifications cause metabolic reprogramming." (PMID 36151426, 2023). "Given that the presence of ER correlates with an upregulation of AR’s tumor suppressor function, trial NCT05065411 will target CDK4/6 to inhibit cell growth and proliferation while modulating AR’s activity to induce tumor suppression." (PMID 38067367, 2023). "Although more effective AR antagonists have evolved, tumor cell resistance has also evolved, culminating in the almost inevitable progression to fatal CRPC." (PMID 37361598, 2023). "Recent studies have highlighted the effects of AR signaling on immune cell function and immune-mediated anti-tumor responses within the tumor microenvironment." (PMID 37646236, 2023).
tumor (continued). "An increasing number of ncRNAs have been identified to be involved in epigenetic modifications, tumor metabolism and AR regulation, which are all closely related to the occurrence and progression of CRPC." (PMID 36674820, 2023). "While lacking real-world confirmation, preclinical studies showed that maximal inhibition of the androgen receptor (AR) via an AR signaling inhibitor (ARSI) resulted in arresting tumor growth and progression while downregulating HRR gene expression." (PMID 37810962, 2023). "It was demonstrated that MPC2 was higher in tumours than in normal tissues and that its expression was driven by AR." (PMID 37086156, 2023). "Here we used enzalutamide-treated patient-derived explant tissues to investigate the impact of AR signaling on MAMs in intermediate-to-high graded tumor tissue (Gleason grade 4 + 3 and 4 + 5)." (PMID 37529692, 2023). "The protein responsible for the tumor-suppression (p14ARF) has been used to regulate the activity of AR and modulate the level of p14ARF in prostate." (PMID 37740236, 2023). "Androgen receptor (AR) is a nuclear receptor that regulates the expression of genes involved in metabolism, immune responses, and tumor progression." (PMID 37537607, 2023). "The combination of AR targeted vaccine and androgen deprivation delayed tumor development in ovariectomized mice." (PMID 37056394, 2023). "This comprehensive review of numerous studies that identified AR-SVs in various tissues reveals that AR-SV expression is pervasive across tumor and non-tumor tissues and in diverse species." (PMID 37626712, 2023). "Our data also confirmed previous studies that showed a high degree of inter-tumor and inter-patient heterogeneity of AR gene rearrangements." (PMID 37636316, 2023). "There were also decreases seen in the expression of AR- and AR-V7-regulated genes in RNA extracted from the tumor tissues, though only the decreases in TMPRSS2 and EDN2 were significant." (PMID 37046780, 2023). "AR’s effects on tumor growth are outlined by the different subtype being studied and the implicated pathways." (PMID 38067367, 2023). "In summary, the results show that hepatoid adenomas characterized by high expression of AR and ER receptors respond positively to antihormonal therapy with drugs that block receptor sites, and treatment leads to complete tumor regression." (PMID 36766353, 2023). "These tumor-recruited B cells promote AR signaling pathways, which further promote the expression of genes associated with metastasis, such as MMP1 and MMP13." (PMID 37666817, 2023). "The transfection experiments revealed three possible problems: firstly, AR plays a role in promoting tumor proliferation and migration in A549." (PMID 37716981, 2023). "For example, the Akt inhibitor ipatasertib re-sensitized androgen-independent cells to antiandrogens, and, when combined with the androgen receptor antagonist enzalutamide, led to remarkable tumor cell growth inhibition, both in vitro and in vivo." (PMID 37296848, 2023). "Further, immunohistochemical analysis confirmed that SBI-46 inhibits AR signaling in xenografted tumor tissues." (PMID 36980655, 2023). "Some studies are combining CDK4/6 inhibitors with AR modulators, the logic behind this being that when ER is positive, AR activation seems to develop tumor suppression activity." (PMID 38067367, 2023). "Glioma cells implanted into nude male and female mice exhibit differential tumor growth; in male animals, tumors are significantly larger and have shorter latency periods, and AR is preferentially detected in tumors propagated in male animals." (PMID 37626712, 2023). "Noteworthy, in that previous study we also detected many additional AR mRNA transcripts in LuCaP 35CR tumor tissue arising from cryptic exon inclusion, intron retention, and alternative 5’ and/or 3’ splice site usage." (PMID 37636316, 2023). "The average size of tumor in AR + was 22.98 ± 14.46 mm (range, 7–70) and in AR– was 23.95 ± 12.09 mm (range, 7–51)." (PMID 36929229, 2023).